EZH2 (enhancer of zeste 2 polycomb repressive complex 2 subunit)
Diseases named in the same sentence as EZH2 in open-access papers (continued):
Sharing a sentence is not in itself a finding about the gene and the disease.
tumor (continued). "EZH2 protein expression in RCC specimens was analyzed by immunohistochemistry using a tissue microarray (TMA) containing RCC tumor tissue and corresponding normal tissue samples of 520 patients." (PMID 20920340, 2010). "EZH2 expression was significantly related to increased tumour cell proliferation, as assessed by Ki-67 expression." (PMID 19773751, 2009). "EZH2 is over-expressed in a variety of tumours, potentially blocking the tumour suppression function of INK4b-ARF-INK4a." (PMID 19954516, 2009). "There was a positive correlation between H3K27me3 expression and WHO grade (P = 0.016), tumor size (P = 0.019), T status (P = 0.024), locoregional progression (P = 0.009) and EZH2 expression (P = 0.036)." (PMID 20028503, 2009). "EZH2 expression was significantly correlated with tumour cell proliferation as assessed by the percentage of Ki-67-positive cells, but not to other clinicopathological variables." (PMID 19773751, 2009). "Of note, tumours with both high EZH2 and BMI1 expression have a HR of 0.6 (95% CI = 0.3 to 1.2) compared with tumours that have high EZH2 and low BMI1, suggesting that the favourable effect of BMI1 overexpression is dominant over the adverse effects of EZH2." (PMID 19099573, 2008). "Grade 3 tumours, which have a worse prognosis than grade 1 and 2 tumours, expressed significantly more EZH2 and less BMI1 than tumours of lower grade (Kruskal-Wallis test, p = 0.001)." (PMID 19099573, 2008). "Depending on accompanying mutations, different genes are likely to be selected for silencing in different tumours, making it difficult to detect a specific epigenetic profile for EZH2 overexpression." (PMID 19099573, 2008). "In the mammary gland, EZH2 expression is coupled with proliferation, but in tumours EZH2 expression is also found in resting cells." (PMID 19099573, 2008). "For EZH2, we find an under-representation of the normal-like subtype in tumours with high EZH2-expression, and an overrepresentation of luminal A type tumours in the group with low EZH2 expression." (PMID 19099573, 2008). "The PcG-target genes INK4A and ARF are not expressed in tumours with high BMI1, but they are expressed in tumours with EZH2 overexpression." (PMID 19099573, 2008). "EZH2-specific cytotoxic T lymphocyte clones specific for two HLA-A0201 epitopes were generated and found to recognise endogenously processed EZH2 in both HLA-matched fibroblasts and tumour cell lines." (PMID 17024127, 2006). "Consistent with recent studies demonstrating overexpression of PcG genes in cancer, we found that both BMI-1 and EZH2 are strongly expressed by a variety of tumours." (PMID 17024127, 2006). "EZH2 represses tumor-suppressive genes, such as E-cadherin, by depositing H3K27me3." (PMID 41596524, 2026). "Firstly, although we have demonstrated through various experimental approaches that OLFML2A influences tumor cell cycle progression and suppresses apoptosis via the regulation of EZH2, the upstream regulatory networks and detailed molecular mechanisms remain insufficiently understood." (PMID 41607539, 2026). "In ALM, where canonical oncogenic mutations such as BRAF V600E and NRAS Q61 are less frequent, EZH2-driven epigenetic mechanisms may play an even more dominant role in tumor initiation and progression." (PMID 42220432, 2026).
tumor (continued). "Elevated EZH2 expression is consistently observed in metastatic HSPC and CRPC compared to benign and primary prostate tissue, and is associated with poor clinical outcomes, including increased recurrence risk, tumor aggressiveness, and reduced survival." (PMID 41601922, 2026). "Interestingly, inhibition of EZH2 has shown promising tumor-suppressive effects in both preclinical and clinical studies." (PMID 41552643, 2026). "For instance, it has been reported that inhibiting miR-363-3p or overexpressing EZH2 could partially reverse the anti-tumor effects of MALAT1 depletion, underscoring the functional axis of MALAT1/miR-363-3p/EZH2 in CRC progression." (PMID 40871106, 2025). "EZH2 inhibitors exert multifaceted effects on tumor immunity." (PMID 41463268, 2025). "Furthermore, decreased levels of STAT2 hampered the anti-tumor immune response in luminal BC by affecting the activation of type I IFN signaling upon inhibition of EZH2." (PMID 40707929, 2025). "PRC2 can also promote carcinogenesis by EZH2-mediated silencing of tumor suppressor genes." (PMID 40678543, 2025). "Leveraging advanced bioinformatics techniques, the identification of 12 crucial genes (ETNK1, BICRA, IL-1R1, KDM3A, ARID2, GSK3β, EZH2, NOTCH1, SMARCA4, FOS, CREB1, CASP3) associated with the tumor-suppressing miR-101-3p network stands out as a notable achievement." (PMID 40074445, 2025). "Additionally, both IHC and Western blot analysis provided strong evidence that Capsanthin effectively downregulates the expression of EZH2 and N-glycosylated PD-L1 in tumor cells within the animal model." (PMID 40038276, 2025). "The overexpression of EZH2 and tumor invasion or metastasis has been confirmed." (PMID 40535805, 2025). "Unlike the LN2A model, a notable distinction in the SNL models is the genetic removal of the Lkb1 tumor suppressor, which has previously been linked to histologic transdifferentiation and increased H3K27 methyltransferase activity in the LUSC cells via EZH2 expression." (PMID 40327401, 2025). "For example, understanding EZH2’s role in cell proliferation and tumor progression may lead to specific inhibitors targeting this gene." (PMID 40018411, 2025). "To investigate whether squamocin could inhibit tumor growth by targeting the EZH2‐MYC axis in vivo, we generated a nude mouse xenograft model of HNSCC with stable EZH2 overexpression." (PMID 39823459, 2025). "After correction for multiple testing, 26 shared factors were highlighted in both analyses: for example, tumor status was associated with decreased methylation at binding sites of TCF7L2 and EZH2, likely reflecting methylation changes characteristic for CRC genesis in general." (PMID 40102611, 2025). "Second, while we highlight EZH2-mediated PTEN silencing, other resistance mechanisms—such as mutations in EGFR or downstream effectors, epigenetic regulation of additional tumor suppressors, and alternative survival pathways—may contribute." (PMID 41156200, 2025). "Additionally, EZH2 inhibits hepatocyte aging and promotes tumor cell survival, potentially facilitating tumor progression by modulating inflammatory responses." (PMID 40018411, 2025). "Targeting EZH2, genetically or pharmacologically, increased GATA6 expression and reduced tumor aggressiveness, suggesting that EZH2 inhibitors could be a therapeutic strategy to induce a less aggressive, more therapy-susceptible PDAC subtype." (PMID 40699746, 2025). "Additionally, inhibiting EZH2 reduced tumor growth and CSC self-renewal and increased chemosensitivity to 5-FU in CRC patient-derived xenograft models." (PMID 40076613, 2025). "EZH2, a histone methyl transferase subunit of a Polycomb repressor complex, is recurrently mutated or highly expressed in several cancers, including ACC and its deregulation is associated with tumor proliferation and worse patient outcomes." (PMID 40229247, 2025).
tumor (continued). "This insight opens up promising avenues for enhancing the efficacy of cellular therapies by engineering T cells with gain-of-function EZH2 mutants, potentially enabling these cells to better navigate the metabolic challenges posed by the tumor milieu and resist pharmacological stressors." (PMID 40739089, 2025). "For example, high plasma H3K27me3 levels may warrant further analysis to confirm tumour EZH2 overexpression and PRC2 dependency." (PMID 40968252, 2025). "Moreover, targeting EZH2 in head and neck cancer can enhance anti-tumor immunity and overcome anti-PD-1 resistance." (PMID 40028035, 2025). "Furthermore, in most tumors, EZH2 expression is positively correlated with T-cell dysfunction, which facilitates the immune evasion of tumor cells leading to drug resistance." (PMID 40701777, 2025). "EZH2 overexpressed in tumor cells can inhibit T cell activation by upregulating PD-L1 expression." (PMID 40959108, 2025). "Conversely, EZH2, the catalytic subunit of Polycomb Repressive Complex 2, mediates gene silencing through H3K27me3 modification and is frequently overexpressed in advanced disease, promoting tumor metastasis and resistance to therapy." (PMID 40959108, 2025). "From the aging perspective, an older patient’s immune system is already less responsive; if a tumor upregulates EZH2 and thereby suppresses antigen presentation or chemokine production, the immunosurveillance might be especially ineffective." (PMID 40918525, 2025). "In addition, mutation or inactivation of the EZH2 gene in myelodysplastic syndrome and T-cell acute lymphoblastic leukemia (T-ALL), where its tumor suppressor role is strongly supported." (PMID 40042761, 2025). "Therefore, we proposed that combinatorial inhibition of EZH2 with mTORC1 inhibition would provide superior anti-tumor efficacy." (PMID 40832297, 2025). "Furthermore, we investigate the anti-tumor effects of combining EZH2 degrader with anti-PD-1, an immune checkpoint inhibitor, focusing on immune cell interactions and underlying mechanisms." (PMID 40308579, 2025). "Furthermore, EZH2 has been identified as a critical driver in reprogramming the tumor microenvironment, making it an appealing therapeutic target." (PMID 40038276, 2025). "Recent studies have increasingly highlighted EZH2 as a key driver of tumor progression." (PMID 40042761, 2025). "Additionally, it highlights the potential therapeutic application of EZH2 inhibitors in treating CRACD-inactivated SCLC tumor cells." (PMID 41353272, 2025). "EZH2 inhibition could enhance anti-tumor immunity and is effective in improving immunotherapy, showing its property in tumor immune escape and immunosuppressive function." (PMID 40028035, 2025). "Given its role in promoting aggressive tumor fates or therapy resistance, our findings suggest that targeting EZH2 may be a viable strategy to combat EGFR-TKI resistance." (PMID 40414926, 2025). "Upon a thorough investigation of EZH2 as a prospective therapeutic target for human cancer, its significance in cancer progression has been meticulously investigated and enhanced, earning its recognition as a prime focus in tumor therapy." (PMID 40028035, 2025). "EZH2 was shown to be amplified in 10–15% of tumours proposing that it results in tumour formation." (PMID 40011240, 2025). "However, inhibition of EZH2 in MB must be approached cautiously, as inhibition of EZH2 can lead to Gfi1 upregulation through epigenetic remodeling, promoting tumor progression in MYC-driven Group 3 MB, supporting a nuanced role for EZH2 in MB." (PMID 40556679, 2025).
tumor (continued). "Pharmacologic inhibition of EZH2 has demonstrated anti-tumor efficacy in preclinical models, including cellular growth arrest, induction of apoptosis, and neuronal differentiation, as well as delayed tumor progression in murine xenografts." (PMID 40896427, 2025). "In the multivariate Cox regression analysis, after adjusting for age, sex, tumor grade, and EZH2 expression levels, high EZH2 expression remained significantly associated with an increased risk of poor overall survival in HCC patients (Hazard ratio = 1.86, p = 0.0007)." (PMID 41209556, 2025). "Moreover, such phosphorylation of EZH2 by AMPK caused upregulation of PRC2 target genes, many of which are known tumor suppressors thereby suppressing the growth of tumor cells." (PMID 40289112, 2025). "Oncologically, canonical EZH2 overexpression upregulates cell-cycle progression genes including cyclins and cyclin-dependent kinases leading to increased rates of cell division and higher mitotic indices within tumor cell populations." (PMID 40766612, 2025). "Similarly, EZH2 expression was associated with tumor-infiltrating immune cells, and epigallocatechin-3-gallate (EGCG) was determined to be the most potent inhibitor of EZH2." (PMID 40881869, 2025). "BAP1 EZH2 overexpression suppresses tumor-suppressor genes and facilitates immune exclusion." (PMID 40661151, 2025). "Additionally, EZH2 maintains a stem-like cell population within the tumor, which is thought to drive tumor progression and metastasis." (PMID 40766612, 2025). "Conversely, established AML cells rely on EZH2 to repress differentiation-inducing or tumour-suppressive pathways, thereby preserving a leukemic stem-like state; accordingly, EZH2 inactivation downregulates AML maintenance programs without reactivating HOX loci." (PMID 40651916, 2025). "This review systematically elucidates the expression profiles, signaling pathways, and the immune checkpoint molecule regulatory mechanisms localized on the NK cell membrane (e.g., NKG2A, KIRs, and TIGIT) or intracellularly (e.g., BIM, Cbl-b, and EZH2) during tumor immune evasion." (PMID 40463500, 2025). "The inhibitory effect of Capsanthin on EZH2 observed in our study suggests it may interrupt these pathways, potentially sensitizing tumor cells to immune responses." (PMID 40038276, 2025). "Additionally, the tumor tissues were homogenized, and the expression levels of EZH2 and PD-L1 were analyzed using Western blotting." (PMID 40038276, 2025). "Most (n = 19/20, 95.0%) PD-L1-expressing tumour cells showed EZH2 immunonegativity." (PMID 40310411, 2025). "Similarly, dysregulation of histone methyltransferase EZH2 has been involved in tumor-extrinsic resistance." (PMID 40554927, 2025). "For instance, elucidating the role of EZH2 in cell proliferation and tumor progression may lead to the creation of inhibitors targeting this protein." (PMID 40018411, 2025). "EZH2 also can regulate cytokines and chemokine in the tumor microenvironment." (PMID 40959108, 2025). "Additionally, IκBζ suppresses Cxcl9, Cxcl10, and Ccl5 expression via HDAC3 and EZH2, which impairs the recruitment of NK and CD8+ T cells into the tumor, causing resistance to α-PD-1 immunotherapy in mice." (PMID 40562773, 2025). "Furthermore, tumor immunostaining showed that EZH2 inhibition reduced cell proliferation (MKI67), increased cell death (cleaved Caspase-3 [CC3]), and restored MHC-I expression in CRPR2 tumors." (PMID 41353272, 2025). "Further in vivo studies will better clarify CSC inhibition and assess whether combining mCHT with EZH2- or STAT3-targeted agents could improve long-term tumor control." (PMID 41516003, 2025). "Targeting EZH2 may also be an effective strategy to overcome oxaliplatin resistance, since EZH2 was shown to promote oxaliplatin resistance in CRC cells, while EZH2 inhibitor suppressed tumor growth and sensitized CRC cells to oxaliplatin." (PMID 40076613, 2025).
tumor (continued). "Notably, some of these highly resistant tumours expressed high levels of targetable epigenetic enzymes, such as EZH2." (PMID 40968252, 2025). "Inhibition of EZH2 can positively activate the immune system toward tumor suppression." (PMID 40959108, 2025). "We hypothesize that the high plasticity of RMC in conjunction with EZH2 inhibition by tazemetostat allowed tumor cells to metastasize to the CNS by acquiring a glial phenotype imparting a survival advantage in the unique milieu of the cerebellum." (PMID 39833894, 2025). "Moreover, EZH2 inhibitor reduced tumor burden and prolonged the survival of the mice transplanted with MDS cells." (PMID 39881418, 2025). "Meanwhile, EZH2 inhibition enhanced natural killer cell-mediated tumor growth inhibition by re-expressing C-X-C motif chemokine ligand 10 and enhancing natural killer cell migration and recruitment to tumor sites." (PMID 40028035, 2025). "Mutations in EZH2, most notably the Y646F hotspot substitution in the SET domain, enhance its methyltransferase activity, leading to increased global H3K27me3 levels and repression of tumor suppressor genes." (PMID 40664798, 2025). "Alternatively, this could reflect tumor cell heterogeneity, where UTX and EZH2 serve distinct roles in different tumor cell populations." (PMID 40042761, 2025). "Several lncRNAs act as oncogenes by recruiting EZH2 to repress tumour suppressors." (PMID 41463281, 2025). "Consequently, a marked decrease in EZH2 protein was also detected in tumor cells following IFN-γ treatment." (PMID 41252204, 2025). "Recent studies have suggested that EZH2 may promote tumor immune evasion by inducing the release of immunosuppressive cytokines and chemokines from tumor cells." (PMID 41209556, 2025). "FOXO1, as a critical tumor suppressor, antagonizes the function of the epigenetic repressor EZH2." (PMID 40396172, 2025). "By contrast, EZH2 acts as an oncogene, with its overexpression driving tumor aggressiveness." (PMID 40959108, 2025). "This noncanonical function of EZH2, which operates independently of its methyltransferase activity, is linked to enhanced tumor cell proliferation and inhibition of apoptosis." (PMID 41413688, 2025). "By downregulating EZH2 expression, Capsanthin can inhibit tumor growth." (PMID 40038276, 2025). "The contributions of regulatory mechanisms and genetic targets contributing to these anti-tumor effects may be critical to understanding how Ezh2 treatment could be best utilized in the treatment of SHH MB patient segments." (PMID 41278839, 2025). "In addition, overexpressed DLEU2 was also reported to promote tumor growth and progression via targeting the EZH2 in HBV-related HCC." (PMID 40625740, 2025). "In addition, UNC1999 can reactivate the sensitivity of bladder cancer tumor cells to radiation therapy by decreasing the expression of EZH2." (PMID 40042761, 2025). "Further assessment demonstrated that the expression of necroptosis-related genes, including FADD, MLKL, TLR2, PGAM, HMGB1, CXCL 1, TRAF2, and EZH2, was elevated in tumor tissue, while FAS, RIPK1, RIPK3, TLR3, TNFRSF, ALDH2, and NDRG2 were upregulated in normal intestinal tissues." (PMID 40959081, 2025). "This may be explainable by the upregulation of EZH2 in SMARCB1-deficient tumours, which enhances CXCR4 expression through the repression of the tumour-suppressive microRNAs miR-622 and miR-9." (PMID 40422882, 2025). "Furthermore, the inhibition of EZH2 results in the reactivation of tumor suppressor genes and the inhibition of tumor growth, suggesting that EZH2 is a promising therapeutic target." (PMID 40427514, 2025). "Similarly, it has been reported that EZH2 inhibitors can reprogram the tumor microenvironment and enhance T-cell-mediated anti-tumor immunity, suggesting a translational synergy with immunotherapy." (PMID 41335282, 2025). "EZH2 in cancer cells can regulate NK cell activation in the tumor microenvironment." (PMID 40959108, 2025).